IL9R (interleukin 9 receptor )
Synonyms: CD129; IL-9R
Gene: Protein-coding gene on chromosome Y (57,184,216 to 57,199,537, forward strand). Ensembl gene ENSG00000292373.
Diseases named in the same sentence as IL9R in open-access papers:
IL9R is named in the same sentence as 50 diseases in open-access papers, as found by Europe PMC text mining. Sharing a sentence is not in itself a finding about the gene and the disease. The quoted sentences say what the papers report.
asthma (7 papers, 2013 to 2024). "The most precise role of IL-9 was found to be associated with human allergic inflammation, both IL-9 and IL-9R was found to be genetically linked to human asthma." (PMID 31164892, 2019). "IL-9 found to be associated with human conditions, such as allergy and asthma, as both IL-9 and IL-9R found to have genetic association with human asthma." (PMID 31164892, 2019). "Nonetheless, the genetic association studies identified the association of IL-9 and IL-9R with human asthma, which was further validated in mouse model of allergic inflammation in asthma." (PMID 29867972, 2018). "IL-9 is known to play crucial role in allergic inflammation in asthma as both IL-9 and IL-9R were shown to be genetically associated with the disease." (PMID 28993609, 2017). "The authors showed that a IL9R allele – sDF2*10 – was more likely to be transmitted among patients with asthma and was found homozygotic among asthma patients more often than expected." (PMID 24260251, 2013). "Both IL-9 and IL-9R polymorphism are found to be genetically associated with asthma." (PMID 29867972, 2018). "In addition, elevated mRNA expression levels of IL-9 and IL-9 receptor (IL-9R) were detected in patients with asthma." (PMID 39175819, 2024). "In patients with asthma, IL-9R is expressed by both lung mast and polymorphonuclear cells." (PMID 28187441, 2017).
Allergy (4 papers, 2017 to 2025). An allergy is an immune response or reaction to substances that are usually not harmful. "We found that the absence of IL-9R signalling conferred resistance to both infection and allergy, as indicated by the reduced fungal load and decreased inflammatory lung pathology in infection as well as in ABPA." (PMID 28090087, 2017).
psoriasis (4 papers, 2013 to 2025). An autoimmune condition characterized by red, well-delineated plaques with silvery scales that are usually on the extensor surfaces and scalp. "Collectively, both patients with psoriasis and psoriatic animal models show an excessive expression of IL-9 and IL-9R and an altered frequency of Th9 cells, suggesting that IL-9 promotes psoriasis and PsA development." (PMID 40771819, 2025). "IL-9R expression was increased in the dermis—particularly at the dermal–epidermal junction—in patients with psoriasis." (PMID 40771819, 2025). "Among skin diseases, it was reported that the patient’s skin with psoriasis expressed a higher number of IL-9R–positive cells and the patient’s skin with atopic dermatitis expressed higher IL-9 mRNA compared with the normal skin." (PMID 37398641, 2023). "In K5.hTGF-β1 transgenic mice, exhibiting a psoriasis-like phenotype, we found increased IL-9R and IL-9 expression in the skin and intradermal IL-9 injection induced Th17-related inflammation." (PMID 23335955, 2013). "Similarly, K5.hTGF-β1 transgenic (psoriasis-prone) mice exhibited a higher expression of IL-9 and IL-9R in the skin compared to control mice." (PMID 40771819, 2025). "The involvement of IL-9 in human autoimmunity has been studied in psoriasis, where it was shown that IL-9 receptor (IL-9R) is increased in lesioned compared to healthy skin, and in lupus erythematous, where IL-9 was reported to be highly expressed in the serum." (PMID 32375811, 2020). "In addition, we observed that IL-9R expression in lesional skin from psoriasis patients was markedly higher than in healthy skin from control subjects." (PMID 23335955, 2013). "In addition, we studied IL-9R expression in psoriatic skin lesions and on CD4+ T cells and the effect of IL-9 on IL-17A production in cultured human peripheral blood mononuclear cells or CD4+ T cells from psoriasis patients." (PMID 23335955, 2013).
lymphoma (3 papers, 2014 to 2016). A malignant (clonal) proliferation of B- lymphocytes or T- lymphocytes which involves the lymph nodes, bone marrow and/or extranodal sites. "Concordant with in vivo observations, the expression of IL-9R in lymphoma cell-lines was confirmed by RT-PCR and western blot analysis, respectively." (PMID 27364124, 2016). "IL-9R was expressed in both mRNA and protein levels in the five lymphoma cell lines, including LY1, LY8, MINO, SP53 and Jurkat." (PMID 27364124, 2016). "IL-9R expression was demonstrated for both mRNA and protein levels within the five lymphoma cell-lines, including LY1, LY8, MINO, SP53 and Jurkat." (PMID 27364124, 2016). "In addition, deletion of IL9R may affect JAK-STAT signaling in response to IL9, which is another pathway important in normal B cells and lymphomas." (PMID 25123191, 2014).
Autoimmunity (2 papers, 2018 to 2020). The occurrence of an immune reaction against the organism's own cells or tissues. "Moreover, IL-9R-deficient mice immunized with MOG develops severe EAE and Tregs isolated from IL-9R-deficient animals were shown to have poor suppressive function, suggesting that IL-9 regulates Tregs suppressive functions in autoimmunity." (PMID 29867972, 2018).
Azoospermia (2 papers, 2019 to 2020). Absence of any measurable level of sperm,whereby spermatozoa cannot be observed even after centrifugation of the semen pellet. "Deletion of IL9R or other adjacent loci in the long-arm pseudoautosomal region might be responsible for some phenotypic features associated with Yq deletions, such as short stature, azoospermia, learning disabilities, and facial dysmorphism." (PMID 33344636, 2020). "It was speculated that the deletion of IL9R or other adjacent loci in the long-arm pseudoautosomal region might be responsible for some phenotypic features associated with Yq deletions, such as short stature, azoospermia, learning disabilities, and facial dysmorphism." (PMID 31828149, 2019).
breast carcinoma (2 papers, 2020 to 2023). "Concerning protein expression in cancer, IL9R significantly enriched in endometrial cancer compared to renal cancer, breast cancer, and other malignancies." (PMID 33329510, 2020). "Because 4T1 breast cancer cells did not express IL9R on their surface, the therapeutic effect of IL9 therapy on macrophage-enriched 4T1 breast cancer was also evaluated." (PMID 36968220, 2023).
carotid atherosclerosis (2 papers, 2013). A thickening and loss of elasticity of the walls of carotid arteries that occur with formation of atherosclerotic plaques. "Here we have examined IL-9 and IL-9 receptor (IL-9R) systemically and locally in patients with coronary and carotid atherosclerosis." (PMID 24023645, 2013). "Carotid lesion samples from patients with asymptomatic and symptomatic carotid atherosclerosis had markedly increased expression of IL-9 and IL-9R as compared with samples from non-atherosclerotic vessels (common iliac artery)." (PMID 24023645, 2013).
colitis (2 papers, 2018 to 2021). Inflammation of the colon. "In oxazolone-mediated colitis model also there was an increase in the expression of IL-9 and IL-9R by intestinal epithelial cells." (PMID 29881387, 2018). "Moreover, abundant IL-9R expressing intestinal epithelial cells were observed in the gut mucosa of UC patients indicating the role of IL-9 and Th9 cells in promoting colitis." (PMID 29881387, 2018). "Several genes such as Gata3, Itk, Ccl8, Ccl22, Ccr4, Crlf2, Il9r, Il1rl1, and Arg2 are regulated concordantly in T-cell transfer colitis, acute DSS colitis and the time point representing high inflammation in the DSS time course." (PMID 34136502, 2021).
colorectal cancer (2 papers, 2021 to 2022). A primary or metastatic malignant neoplasm that affects the colon or rectum. "Th9 cells promote the expansion of CD8+ T cells in an IL-9R-dependent manner in colorectal cancer." (PMID 33816497, 2021).
diffuse large B-cell lymphoma (2 papers, 2014 to 2021). "IL-9R was markedly overexpressed in diffuse large B-cell lymphoma tissues compared to their counterparts, and it was associated with several adverse prognostic parameters." (PMID 24722378, 2014). "Wang and colleagues reported elevated serum levels of IL-9 in B cells from non-Hodgkin’s lymphoma and diffuse large B-cell lymphoma (DLBCL) patients, along with high levels of IL-9R expression in tumoral tissues that correlate with adverse prognostic markers of the disease." (PMID 34944921, 2021).
Hodgkins lymphoma (2 papers, 2018 to 2022). A heterogeneous group of malignant lymphoid neoplasms of B-cell origin characterized histologically by the presence of Hodgkin and Reed-Sternberg (HRS) cells in the vast majority of cases. "In agreement with our data, IL9R has been associated with different inflammatory, autoimmune, and malignant diseases, such as psoriasis lesion, lupus erythematous, and various human leukemias, including T-cell leukemia, megakaryoblastic leukemia, and Hodgkin lymphomas." (PMID 29937515, 2018).
lung carcinoma (2 papers, 2022). "Lastly, elevated expression of IL-9R and Arg1 in tumor lesions is associated with poor prognosis in lung cancer patients." (PMID 35778404, 2022). "High expression of IL9 and IL9R clearly associated with poor survival probability in lung cancer patients." (PMID 35778404, 2022). "Consistent with the data from lung cancer patients, lung macrophages occupied over 75% of the IL-9R+ cells." (PMID 35778404, 2022). "Multiplex-immunohistochemistry was performed to confirm that TAMs in lung cancer patients express IL-9R at the protein level." (PMID 35778404, 2022). "Finally, we performed FACS analysis in the human adenocarcinoma lung cancer cell line A549 to understand if IL-9R is expressed in these tumor cells and detected IL9R expression in A549 cells." (PMID 35514957, 2022). "Thus, blocking IL-9 signaling on lung macrophages, when macrophages are IL-9R+, could be a feasible therapeutic strategy for lung cancer and potentially other lung diseases." (PMID 35778404, 2022).
melanoma (2 papers, 2022 to 2023). A malignant, usually aggressive tumor composed of atypical, neoplastic melanocytes. "Seven days after B16 melanoma injection, mice were treated with nanoparticles containing either Scrambled (Scr)-siRNA or Il9r-siRNA every 72hs." (PMID 35778404, 2022). "Because the B16F10 melanoma cells did not express IL9R on their surface, autocrine IL9 expression did not affect the in vitro proliferation of IL9-B16F10 cells." (PMID 36968220, 2023).
rheumatoid arthritis (2 papers, 2019 to 2021). A chronic, systemic autoimmune disorder characterized by inflammation in the synovial membranes and articular surfaces. "In rheumatoid arthritis (RA), an increased expression of IL-9 and IL-9R is observed in synovial tissue, which also correlates with the degree of tissue inflammation." (PMID 31035677, 2019). "Indeed, high serum levels of IL-9 and soluble IL-9R have been found in rheumatoid arthritis (RA) patients." (PMID 33995403, 2021). "Relative mRNA expression of PU.1, IL-9, IL-17 and IL-9R in control conditions (Th0), Th9- and Th17-inducing conditions in naive and non-naive T cells of healthy donors (HD) and rheumatoid arthritis (RA) patients." (PMID 33995403, 2021).
systemic sclerosis (2 papers, 2018 to 2024). A chronic disorder, possibly autoimmune, marked by excessive production of collagen which results in hardening and thickening of body tissues. "Recently, neutrophils isolated from patients with systemic sclerosis (SSc) express IL-9R and exposure of these neutrophils to rIL-9 can significantly induce NET formation." (PMID 30622982, 2018).
anaphylaxis (1 paper, 2012). An acute hypersensitivity reaction that occurs from exposure to an allergen. "Deficiency in IL-9 or IL-9R attenuates intestinal anaphylaxis, while transgenic expression of IL-9 in the intestine results in local mastocytosis and increased susceptibility to intestinal anaphylaxis." (PMID 22413008, 2012).
anaplastic large cell lymphoma (1 paper, 2022). Anaplastic large cell lymphoma (ALCL) is a rare and aggressive peripheral T-cell non-Hodgkin lymphoma, belonging to the group of CD30-positive lymphoproliferative disorders, which affects lymph nodes and extranodal sites. "The dysregulation of IL-9 and IL-9R could be detected in the biopsy specimens and serum of patients with HL, anaplastic large cell lymphoma (ALCL), and nasal NK/T cell lymphoma." (PMID 35211408, 2022).
atherosclerosis (1 paper, 2013). A disease characterized by the build-up of fatty material and calcium deposition in the arterial wall resulting in partial or complete occlusion of the arterial lumen. "This suggests a role for the IL-9/IL-9R interaction in atherosclerosis, but the functional consequences of these findings are at present unclear." (PMID 24023645, 2013).
autoimmune disease (1 paper, 2022). A disorder resulting from loss of function or tissue destruction of an organ or multiple organs, arising from humoral or cellular immune responses of the individual to their own tissue constituents. "IL9R is a receptor of interleukin 9 (IL-9), which participates in various models of T cell-dependent inflammation and plays an important role in driving the immune responses to autoimmune diseases and chronic inflammation on mucosal surfaces." (PMID 36118358, 2022).
coronary atherosclerosis (1 paper, 2013). Atherosclerosis of the coronary vasculature. "Here we report for the first time increased levels of both IL-9 and IL-9R in patients with carotid and coronary atherosclerosis." (PMID 24023645, 2013). "We examined this hypothesis by various experimental approaches including studies on the expression of IL-9 and IL-9R in patients with carotid and coronary atherosclerosis." (PMID 24023645, 2013).
endometrial cancer (1 paper, 2020). Primary or metastatic malignant neoplasm involving the endometrium (mucous membrane that lines the endometrial cavity). "Similar to IL9, IL9R RNA was also up-regulated in endometrial cancer tissues (UCEC) compared to adjacent normal tissues (n = 265, p < 0.05)." (PMID 33329510, 2020). "Firstly, IL9R RNA was found not relevant to the DFS or OS of endometrial cancer based on a small sample size of data(n = 168) from the TCGA dataset." (PMID 33329510, 2020). "Besides, IL9R, the receptor of IL9, was up-regulated in the endometrium tissue and endometrial cancer tissues as well." (PMID 33329510, 2020).
inflammatory bowel disease (1 paper, 2018). A spectrum of small and large bowel inflammatory diseases of unknown etiology. "In the gut inflammation in inflammatory bowel diseases (IBD), IL-9-producing CD4+ T cells were found to be colitogenic, as gut epithelial cells of ulcerative colitis patients expressed elevated levels of IL-9R." (PMID 29867972, 2018).
Insulin resistance (1 paper, 2025). Increased resistance towards insulin, that is, diminished effectiveness of insulin in reducing blood glucose levels. "To better understand how IL-9 might affect the pathogenesis of diet-induced obesity and insulin resistance, we used mice deficient in IL-9/IL-9R signaling." (PMID 40962954, 2025).
lung adenocarcinoma (1 paper, 2022). A carcinoma that arises from the lung and is characterized by the presence of malignant glandular epithelial cells. "The expression of IL-9R on lung adenocarcinoma cells may permit direct effects of IL-9 on tumor cell proliferation or apoptosis." (PMID 35514957, 2022). "In summary, subsets of tumor infiltrating lymphocytes in the lung as well as lung adenocarcinoma cells express IL9R and may thus be targets for immunomodulatory and cancer promoting effects of IL-9." (PMID 35514957, 2022). "Moreover, our findings demonstrate that anti-IL-9 antibodies markedly suppress tumor growth in vivo and identify IL-9R+ TILs and lung adenocarcinoma cells as targets for IL-9 signaling." (PMID 35514957, 2022).
lupus erythematosus (1 paper, 2022). An autoimmune, connective tissue chronic inflammatory disorder affecting the skin, joints, kidneys, lungs, heart, and the peripheral blood cells. "Previous studies have shown enhanced serum levels of IL-9R in autoimmune conditions (i.e., lupus erythematosus)." (PMID 35204724, 2022).
malaria (1 paper, 2025). Malaria is a serious and sometimes fatal disease caused by a parasite that commonly infects a certain type of mosquito which feeds on humans. "Despite mining numerous publicly available human malaria datasets, we were unable to find a high IL-9R-expressing B cell population that could be correlated with enhanced protection upon pathogen re-exposure." (PMID 40215168, 2025).
multiple sclerosis (1 paper, 2022). A progressive autoimmune disorder affecting the central nervous system resulting in demyelination. "Previous studies have shown IL-9 affects microglia in multiple sclerosis, and IL-9R expression has been detected in human blood monocytes and alveolar macrophages." (PMID 35778404, 2022).
Obesity (1 paper, 2025). Accumulation of substantial excess body fat. "Taken together, during obesity, IL-9 production by CD4 + T cells and ILC2s and IL-9R expression on macrophages are significantly downregulated." (PMID 40962954, 2025). "During diet-induced obesity in mice, the frequencies of IL-9 + CD4 + T cells and ILC2s and IL-9R expression on macrophages are significantly decreased." (PMID 40962954, 2025). "Furthermore, in vivo macrophage depletion resulted in increased frequencies of ILC2s and eosinophils in the adipose tissue of HFD-fed IL-9R KO mice compared with PBS-treated controls, indicating that macrophages are the major target cell types of IL-9 during obesity." (PMID 40962954, 2025).
unstable angina (1 paper, 2013). "To further examine the regulation of IL-9 in atherosclerotic disorders, we analyzed mRNA levels of IL-9 and IL-9R in T cells and monocytes from patients with stable and unstable angina and in healthy controls." (PMID 24023645, 2013). "These new findings further underscore a link between IL-9 and IL-17 and suggest that this link is particularly strong in patients with unstable angina, potentially reflecting up-regulation of IL-9R in T cells from these patients." (PMID 24023645, 2013). "Finally, enhanced expression was also seen at the cellular level with increased levels of IL-9 mRNA and IL-9R in T cells from patients with unstable angina, and for IL-9, this up-regulation was also seen in monocytes." (PMID 24023645, 2013). "T cells from patients with unstable, but not stable angina had significantly increased mRNA expression of IL-9 and IL-9R compared with T cells from healthy controls, and for IL-9, the difference between unstable and stable disease was also significant." (PMID 24023645, 2013).
vaginal candidiasis (1 paper, 2018). "We next evaluated the susceptibility of Il9R−/− mice to vaginal candidiasis." (PMID 30515173, 2018).